USP29 (ubiquitin specific peptidase 29)
Diseases named in the same sentence as USP29 in open-access papers (continued):
Sharing a sentence is not in itself a finding about the gene and the disease.
Stillbirth (1 paper, 2016). Death of the fetus in utero after at least 22 weeks of gestation. "This has been also demonstrated in the bovine lineage: a genomic deletion in the Usp29/Mimt1 region resulted in stillbirth in cows." (PMID 27327533, 2016).
triple-negative breast carcinoma (1 paper, 2024). An invasive breast carcinoma which is negative for expression of estrogen receptor (ER), progesterone receptor (PR), and human epidermal growth factor receptor 2 (HER2). "In triple-negative breast cancer, USP29 was recently reported to be phosphorated and activated by cyclin-dependent kinase 1 (CDK1), and then deubiquitinate and stabilize twist family bHLH transcription factor 1 (TWIST1), which is a key regulator of epithelial-mesenchymal transition." (PMID 38233848, 2024).
cancer (18 papers, 2015 to 2026). A tumor composed of atypical neoplastic, often pleomorphic cells that invade other tissues. "As a deubiquitinase, USP29 participates in the regulation of cancer cell fate by affecting its substrates." (PMID 38233848, 2024). "Since USP29 was reported to regulate the stability of some substrates such as HIF1α and Snail1 in different cancer cells, we also examined the effect of USP29 on these proteins in TNBC." (PMID 36782089, 2023). "USP29 can promote the migration of gastric cancer cells by preventing Snail degradation, thereby maintaining high protein expression of Snail in cancer cells." (PMID 36969062, 2023). "USP29 has recently been reported to play an important role in cancer metabolism, progression, and prognosis (19, –, 22)." (PMID 35638730, 2022). "Immunohistochemical staining of cleaved Caspase 3 in tumor sections revealed that cancer cell apoptosis was increased by Sorafenib treatment but was even higher upon combination of Sorafenib with depletion of USP29." (PMID 34272356, 2021). "Using a publicly available database, we first investigated the expression level of USP29 in several cancer types." (PMID 34072621, 2021). "Previous researchers reported the functions of USP29 and its ability to regulate cancer-related proteins." (PMID 34072621, 2021). "Ubiquitin-specific protease 29 (USP29), a deubiquitinating enzyme, is involved in the occurrence and development of wide variety of cancers." (PMID 34072621, 2021). "We observed that multiple cancer tissues had higher USP29 expression than the corresponding normal tissues." (PMID 34072621, 2021). "USP29 likely represents an advantageous choice of cancer cells owing to its high efficiency to stabilize Snail1 even with relatively low abundance, considering the critical challenges posed at them within chemotherapeutic milieus." (PMID 32968046, 2020). "Having provided several lines of biochemical evidence that USP29 functioned to stabilize Snail1 levels through its deubiquitylation activity, we sought to search for clinical implications of USP29 expression in cancer tissues." (PMID 32968046, 2020). "In light of the recognized notion that the stemness of cancer cells positively correlate with the tumorigenic potentials in vivo, we evaluated the influence of USP29 overexpression on H1299 xenograft growth in nude mice." (PMID 32968046, 2020). "The genomic distance between ECR18 and USP29-Pro is only about 30 kb in length, yet the DNA methylation level changes of the two regions become opposite in the cancer samples: one with hypermethylation and the other hypomethylation." (PMID 26338779, 2015). "In the case of USP29-Pro, changes in the DNA methylation occurred in 1 out of 6 normal and 20 out of 40 cancer samples, resulting in 16.6 and 50% frequencies in the normal and cancer sets, respectively." (PMID 26338779, 2015). "Moreover, the pharmacological inhibition of CDK1 by RO‐3306 markedly decreased the migration, invasion, the efficiency of mammosphere formation, metastasis and sensitized cancer cells to chemotherapeutic drugs in cells with the reconstitution of WT USP29." (PMID 36782089, 2023). "Mounting studies have elucidated the multifaceted roles of USP29 in cancers." (PMID 36373629, 2023). "Finally, USP29 ubiquitinase is a potential novel target for cancer therapy as it provides an upstream hub for MYC and HIF1α." (PMID 37443779, 2023). "Depletion of USP29 in HCT116 by CRISPR-Cas9 system reduced the growth of cancer cells." (PMID 34072621, 2021). "We sought for the clinical implications of USP29 expression in different cancer tissues." (PMID 34072621, 2021). "The oncogenic role of USP29 has recently been explored in a few cancer types." (PMID 34072621, 2021). "Considering the pivotal roles that Snail1 plays during the development of resistance to chemotherapies, we posited that the USP29-Snail1 axis might be exploited by cancer cells in their acquisition of chemoresistance." (PMID 32968046, 2020).
cancer (continued). "Importantly, USP29 levels were induced by chemotherapy and oxidative stress treatments, indicating a novel mechanism exploited by cancer cells to acquire drug resistance and enable metastasis in response to chemotherapies." (PMID 32968046, 2020). "Therefore, USP29 can be used as a new therapeutic target for treating cancer." (PMID 39664521, 2024). "Given the fact that Usp29 knockout mice are viable without noticeable defects, suggesting that USP29 is dispensable for normal development and physiological functions, and specific USP29 inhibitors are likely to cause minimal side effects in cancer treatment." (PMID 38233848, 2024). "Consistently, another group recently reported that USP29 promotes aerobic glycolysis via stabilizing HIF1α to mediate sorafenib resistance in HCC cell lines, suggesting that USP29 may play a key role in the regulation of aerobic glycolysis in different cancer types." (PMID 35307036, 2022). "However, significantly higher expression of USP29 (p = 0.00016) was observed in COAD patients than in other cancer cohorts, strongly suggesting that USP29 might be associated with the progression of CRC." (PMID 34072621, 2021). "USP29 interacts with HIF-1α, reduces its poly-ubiquitination and protects it from proteasomal degradation across multiple cancer cell lines." (PMID 42125859, 2026). "The reported deubiquitinases of MYC include USP22, USP28, USP29, USP36 and USP37, and they enhance cancer stemness via BMI1, LSD1 Snail and CEP63 stabilization, respectively." (PMID 36765885, 2023). "Since USP29 increases cancer cell migration and invasion through TWIST1 in vitro, we further investigated USP29 function in TNBC metastasis in vivo." (PMID 36782089, 2023). "These DUBs (USP22, USP28, USP29, USP36, USP37 and OTUD6A) are observed in stabilizing MYC in cancer cells." (PMID 36765885, 2023). "USP29 stabilizes oncogenic MYC (including c-MYC and N-MYC) and hypoxia-induced factor 1α (HIF1α), which are two major drivers of cancer metabolism in normoxia and hypoxia, respectively, by direct interaction and deubiquitination." (PMID 35307036, 2022). "Similar to other USP29 substrates c-MYC, HIF1α and Snail1, AURKB deregulation often occurs in cancers, implying that USP29 may become a potential target for cancer treatment." (PMID 38233848, 2024). "It is tempting to speculate that the inhibition of USP29 DUB activity will interfere with Snail1 levels and subsequently deter the development of chemoresistance and metastasis in a variety of cancers." (PMID 32968046, 2020). "The knockdown of USP29 significantly decreased the expression of TWIST1, and increased cancer cellular sensitivity to these chemotherapeutic agents both in vitro and in vivo, which could be largely reversed by the reconstitution of TWIST1 in USP29‐depleted cells." (PMID 36782089, 2023). "However, evidence concerning the expression of USP29 in other cancers is currently lacking." (PMID 34072621, 2021). "In contrast, the DNA methylation levels of the other regions, such as USP29-Pro and ECR18, were shown to be more fluctuating in both normal and cancer samples." (PMID 26338779, 2015).
tumor (10 papers, 2020 to 2024). "As expected, the Usp29 homozygous null mice (Usp29−/−) showed a significant decrease in tumor numbers and tumor incidence upon BaP induction." (PMID 38233848, 2024). "Ectopic expression of USP29 promoted, while depletion suppressed the tumor growth in vitro and in vivo mouse model." (PMID 38233848, 2024). "Consisting with the findings obtained in vitro, USP29 knockdown significantly suppressed tumor growth in vivo." (PMID 38233848, 2024). "At last, mouse xenograft tumor models were established using SW620 cells with stable low expression of USP29." (PMID 36373629, 2023). "Expectedly, the depletion of USP29 effectively limited the proliferation of SW620 and HCT116 cells in vitro, and the xenograft tumor models revealed that USP29 downregulation inhibited the proliferation of CRC cells in vivo." (PMID 36373629, 2023). "Silencing USP29 hampered tumor growth, as evidenced by reduced tumor volume and weight (p < 0.01) and diminished positive rate of Ki67 (p < 0.01)." (PMID 36373629, 2023). "Then, the correlation between the expression levels of USP29 and the clinical characteristics of CRC patients was analyzed, and it was found that USP29 expression level was correlated to tumor size, lymph node metastasis, and TNM stage of CRC patients." (PMID 36373629, 2023). "Together, these results uncover a previously unrecognized function of USP29 in tumor progression of TNBC through stabilizing TWIST1." (PMID 36782089, 2023). "Taken together, our study results suggested that USP29 facilitated tumor metastasis and progression and exerted its effect by stabilizing and deubiquitinating Cdc25A." (PMID 34071237, 2021). "On the other hand, the NSG mice with the USP29-depleted cells with reconstituted USP29 had a substantial increase in the volume of tumor (p < 0.0001) and weight (p = 0.0037)." (PMID 34072621, 2021). "In line with our in vitro observations, tumor growth was significantly delayed and tumor weights significantly reduced upon USP29 knockdown and concomitant treatment with Sorafenib." (PMID 34272356, 2021). "Immunohistochemical staining of USP29 and HIF1α on tumor sections confirmed that the siRNA-mediated knockdown of USP29 not only efficiently depleted USP29 but also reduced HIF1α levels." (PMID 34272356, 2021). "We also showed that USP29 played a critical role in Cdc25A-mediated regulation of the cell cycle in cancer cell lines and in tumor progression." (PMID 34071237, 2021). "The tumor xenograft derived from USP29-depleted HCT116 cells showed the reduced volume of the tumor than the scrambled sgRNA control." (PMID 34072621, 2021). "In NSG mice transplanted with USP29-depleted cells, tumor volume was significantly reduced compared with those in mice that received mock control cells and expressed USP29 at endogenous levels." (PMID 34071237, 2021). "In the NSG mice with USP29-depleted cells, tumor growth was substantially reduced compared to mice that injected the scrambled sgRNA control cells (p < 0.0001)." (PMID 34072621, 2021). "On the other hand, transplantation of USP29-depleted cells reconstituted with Cdc25A led to an increased tumor volume." (PMID 34071237, 2021). "Recorded xenograft growth revealed dramatically accelerated increases in tumor volumes incurred by USP29 overexpression, recalling the stimulatory impact of USP29 on tumor spheroid formation." (PMID 32968046, 2020). "Consistently, Western blotting analysis of tumor xenograft samples confirmed elevated Snail1 levels in samples with enhanced USP29 expression." (PMID 32968046, 2020). "In doing this, the same quantities of H1299 cells stably transfected with control or USP29-expressing vectors were subcutaneously inoculated into athymic nude mice to generate tumor xenografts." (PMID 32968046, 2020). "Taken together, these findings strongly suggest that USP29 may promote the tumor formation and progression through stabilization of AURKB." (PMID 38233848, 2024).
tumor (continued). "Importantly, deletion of Usp29 suppressed the mice forestomach tumor formation induced by BaP and Aurkb expression in the tissues." (PMID 38233848, 2024). "Finally, the xenograft tumor model revealed the promotive role of USP29 in the proliferation of CRC cells in vivo." (PMID 36373629, 2023). "Our results demonstrate USP29 promotes tumor progression in TNBC through TWIST1." (PMID 36782089, 2023). "Furthermore, our data suggests that USP29 knockdown reduced the tumor volume of mouse xenograft models." (PMID 34072621, 2021). "Depletion of USP29 in HCT116 cells substantially reduced the tumor volume of mouse xenografts." (PMID 34072621, 2021). "Finally, we demonstrated that USP29 was critical in promoting Cdc25A-dependent cell cycle progression and tumor formation in vivo." (PMID 34071237, 2021). "Moreover, NSG nude mice transplanted with USP29-depleted cells significantly reduced the size of the tumors, whereas the reconstitution of Cdc25A in USP29-depleted cells significantly increased the tumor size." (PMID 34071237, 2021). "USP29 stabilizes MYC and hypoxia-inducible factor 1-alpha (HIF1α); therefore, it enables tumor cells to respond to both normoxia and hypoxia." (PMID 39664521, 2024). "CDK1‐mediated phosphorylation is essential to activate USP29 toward TWIST1 and promote tumor progression in TWIST1 dependent manner." (PMID 36782089, 2023). "USP29 directly binds, deubiquitinates, and stabilizes TWIST1, which in turn promotes TWIST1‐driven tumor progression in TNBC." (PMID 36782089, 2023). "In this present work, we found the correlation between USP29 expression levels and the tumor size, lymph node metastasis, and TNM stage of CRC patients and USP29 upregulation in CRC tissues and cells." (PMID 36373629, 2023). "We subcutaneously injected scrambled sgRNA control, USP29-depleted HCT116 cells, and USP29-depleted cells with reconstituted USP29 into different groups of NSG mice and monitored the tumor growth continuously for 4 weeks." (PMID 34072621, 2021). "To further validate the effect of USP29 on oncogenic transformation, we used USP29-depleted HCT116 cells and performed an in vivo tumor formation assay." (PMID 34072621, 2021). "To corroborate the USP29-mediated effect on Cdc25A-dependent oncogenic transformation in vivo, we transplanted USP29-depleted HeLa cells, USP29-depleted cells reconstituted with Cdc25A, or mock control cells into NSG mice and measured tumor volume on alternate days for four weeks." (PMID 34071237, 2021). "Furthermore, USP29 depletion in HCT116 cells decreased migration, invasion, and tumor formation." (PMID 34072621, 2021).
adenocarcinoma (1 paper, 2020). A common cancer characterized by the presence of malignant glandular cells. "We therefore switched to the opposite approach of overexpression and thus generated H1299 and H1975 adenocarcinoma cell lines stably overexpressing USP29, which displayed consistent upregulation of Snail1 levels." (PMID 32968046, 2020).
neurological diseases (1 paper, 2023). "USP29 is a deubiquitinating enzyme important during the development of tumors, neurological diseases, and viral immunity." (PMID 37304282, 2023).
USP29 also shares sentences with these, for which no sentence is quoted: non-small cell lung carcinoma (2 papers); prostate carcinoma (2); B-cell lymphoma (1); cervical cancer (1); diffuse large B-cell lymphoma (1); lymphoid neoplasm (1); metabolic dysfunction-associated steatotic liver disease (1); osteosarcoma (1); squamous cell carcinoma (1).